SEPTIN7 (septin 7)
Diseases named in the same sentence as SEPTIN7 in open-access papers:
SEPTIN7 is named in the same sentence as 66 diseases in open-access papers, as found by Europe PMC text mining. Sharing a sentence is not in itself a finding about the gene and the disease. The quoted sentences say what the papers report.
glioma (15 papers, 2015 to 2023). A benign or malignant brain and spinal cord tumor that arises from glial cells (astrocytes, oligodendrocytes, ependymal cells). "The overexpression of Septin7 caused the inhibition of migration in glioma cells, while the opposite effect prevailed in breast cancer cell lines." (PMID 37508490, 2023). "As the expression of Septin7 in various glioma cell lines was lower than that in normal brain cells, a research group revealed that the overexpression of Septin7 significantly inhibited LN18 cell migration and chemotaxis, which was induced by IGF-1." (PMID 37508490, 2023). "SEPTIN7 is downregulated in gliomas, and its decreased expression negatively correlates with increased tumor grade." (PMID 35646664, 2022). "Septin 7 expression in various glioma cell lines was found to be reduced compared to normal human glia cells, while overexpression suppressed glioma cell migration." (PMID 31857849, 2019). "It was also proven that increased Septin7 expression could depolymerize actin filaments, thus obstructing glioma cell migration." (PMID 37508490, 2023). "The role of septin 7 in cancers varies depending upon the cancer type: it increases the migration and invasion of breast cancer cells, but inhibits the proliferation, migration, and invasion of glioma cells." (PMID 32516969, 2020). "Thus, interaction of septin 7 with cofilin phosphate modulates the homoeostasis of actin and cytoskeletal motility, providing a promising candidate for new therapeutic approaches to the treatment of gliomas." (PMID 29602250, 2018). "In glioma and PTC, septin 7 negatively regulated the growth and progression of tumour." (PMID 29602250, 2018).
breast carcinoma (14 papers, 2016 to 2024). "Septin 7 can also contribute to cancer development and it was previously implicated in cell migration and invasion in breast cancer cell lines." (PMID 38203360, 2023). "On the contrary, reducing the expression of Septin2 and Septin7 resulted in reduced proliferative migration, and invasion in human breast cancer cell lines." (PMID 37508490, 2023). "Our study demonstrates the importance of septin 7 for the migration of lung cancer cells, and confirms previous findings about its role in breast cancer cells." (PMID 32516969, 2020). "Knockdown of septin 7 decreased cancer cell migration of MDA-MB-231 breast cancer cells, H1299, and A549 lung cancer cells." (PMID 32516969, 2020). "Firstly, we tested the effect of knockdown of septin 7 on the migration of breast cancer cells and lung cancer cells." (PMID 32516969, 2020). "However, higher expression levels of septins 2/7 in breast cancer and hepatocellular carcinomas (septin 7) hint towards a putative role also as oncogenes in those cancer types." (PMID 31857849, 2019). "Septin 7 is a member of a family of GTP-binding proteins that have the potential to interact with and to stabilize PSD9568, however, also have the ability to activate the MEK/ERK pathway at least in MDA-MB-231 human breast cancer cells." (PMID 29844452, 2018).
lung carcinoma (5 papers, 2020 to 2023). "To analyze the role of Septin7 in tumor development, we decided to establish a Septin7-dependent in vivo mouse model of lung adenocarcinoma formation, the major form of lung cancer associated with activating mutations in the Kras oncogene." (PMID 35071236, 2021). "Interestingly, a recent multi-omics study correlated low SEPTIN7 expression levels and an intronic single-nucleotide polymorphism in the SEPTIN7 gene with higher survival rates for long-term former smoking lung cancer patients." (PMID 35071236, 2021). "We also demonstrate that knockdown of the cytoskeletal protein septin 7 decreases the motility of lung cancer cells, and identify septin 7 as a downstream effector for ERK3-induced cancer cell migration." (PMID 32516969, 2020). "As expected, overexpression of ERK3 increased migration (compare siCtrl/ERK3 to siCtrl/empty vector) and knockdown of septin 7 decreased migration of lung cancer cells (compare siSEPT7/empty vector to siCtrl/empty vector)." (PMID 32516969, 2020). "Importantly, the knockdown of septin 7 abolished the ability of ERK3 to promote lung cancer cell migration (compare siSEPT7/ERK3 to siSEPT7/empty vector)." (PMID 32516969, 2020). "Importantly, we have found that septin 7 is a downstream mediator of the migration-promoting ability of ERK3 in lung cancer cells." (PMID 32516969, 2020). "Septin 7 plays a downstream effect in ERK3-induced migration of cancer cells, and its deletion abolishes the ability of ERK3 to promote lung cancer cell migration and invasion." (PMID 37080972, 2023).
Alzheimer disease (4 papers, 2018 to 2022). A progressive, neurodegenerative disease characterized by loss of function and death of nerve cells in several areas of the brain leading to loss of cognitive function such as memory and language. "Septin 7 is linked to Alzheimer’s disease, schizophrenia, neuropsychiatric erythematosus lupus and different tumors." (PMID 31857849, 2019). "Also, Septin7 deficiency alters the morphology of mature neurons, leading to neurological disorders such as Alzheimer’s disease, schizophrenia, and neuropsychiatric lupus erythematosus." (PMID 35929607, 2022).
autoimmune disease (4 papers, 2014 to 2023). A disorder resulting from loss of function or tissue destruction of an organ or multiple organs, arising from humoral or cellular immune responses of the individual to their own tissue constituents. "With our findings, we contribute to gaining deeper insights into the migratory behavior and septin 7-dependent cytoskeletal reorganization of immune cells in organ-specific autoimmune diseases." (PMID 32211402, 2020). "The aim of our study was to extend the knowledge about the role of septin 7 in lymphocytes and in the context of a spontaneous autoimmune disease." (PMID 30120291, 2018). "Septin 7 has a corset-like function providing cell compression and rigidity, an interesting feature regarding pathogenesis of autoimmune disease, where activated immune cells cross anatomical barriers." (PMID 24614191, 2014). "Amongst those, especially the identification of DOCK8 as a novel septin 7 interaction partner was a promising finding that could help to elucidate pathomechanisms in autoimmune diseases in our opinion." (PMID 30120291, 2018). "Moreover, we gained information about the role of septin 7 and its novel interactor DOCK8 in autoimmune disease." (PMID 30120291, 2018). "However, the impact of expression changes or functional deviations of septin 7 in lymphocytes in course of autoimmune disease was not described to date." (PMID 30120291, 2018).
asthenospermia (2 papers, 2018 to 2021). "In the patients with asthenospermia the percentage of septin 7 deficient signals was significantly higher compared to controls, and the degree of asthenospermia appeared to be related to the percentage of defective septin 7 signals." (PMID 29602250, 2018).
autoimmune uveitis (2 papers, 2014 to 2018). An autoimmune form of uveitis (disease). "Our previous finding of decreased septin 7 expression in blood-derived lymphocytes in ERU, a spontaneous animal model for autoimmune uveitis in man, extended the role of septin 7 to a potential key player in autoimmunity." (PMID 30120291, 2018). "The detection of septin 7 downregulation in lymphocytes of cases with spontaneous autoimmune uveitis is a very interesting finding in our opinion and its functional pathogenetic role in ERU merits further analysis." (PMID 24614191, 2014). "However, further studies are necessary to analyze possible connection of altered septin 7 expression and transmigration of cells in autoimmune uveitis." (PMID 24614191, 2014).
Autoimmunity (2 papers, 2018 to 2023). The occurrence of an immune reaction against the organism's own cells or tissues. "Altogether, the different clinical phenotypes reported in patients with anti-septin-3, anti-septin-5 or anti-septin-7 autoimmunity so far suggest that these autoantibodies may be markers for different clinical presentations." (PMID 36997937, 2023).
colon carcinoma (2 papers, 2013 to 2018). "The effect of CR overexpression on septin 7 levels was investigated in SPC212 cells, as well as in the CR-expressing colon carcinoma cell line HT-29, previously shown to negatively modulate CR expression in a Bt-dependent way." (PMID 29699512, 2018).
adenoma (1 paper, 2021). A neoplasm arising from the epithelium. "Another possibility is that the appearance of this novel (non-adenoma) tumor cells is caused by Kras activation combined with genetic instability caused by the loss of Septin7." (PMID 35071236, 2021). "Control mice sacrificed in the age of 4 weeks display a bronchiolo-alveolar hyperplasia with multiple adenomas, whereas the Septin7-deficient animals of the same age are normal or show only a weak multifocal brochiolo-alveolar hyperplasia." (PMID 35071236, 2021). "Analyses of control mice sacrificed at the age of 4 weeks displayed a bronchiolo-alveolar hyperplasia with multiple adenomas, whereas lungs of Septin7-deficient animals of the same age were unremarkable or showed only a weaker multifocal brochiolo-alveolar hyperplasia." (PMID 35071236, 2021). "A possible explanation is that the growth of adenoma was inhibited in the absence of Septin7 and other cell types with activated Kras form tumors with a slower kinetics." (PMID 35071236, 2021). "These “late” (slow growing) adenomas could result from cells adapted to Septin7 ablation or could also arise from a minor cell population with Cre-driven recombined Kras but without Cre-driven Septin7 deletion." (PMID 35071236, 2021).
astrocytic tumor (1 paper, 2022). A glial tumor of the brain or spinal cord showing astrocytic differentiation. "EGFR is the most frequently amplified oncogene in astrocytic tumors; expression of genes SRI, NPTX2, MEST, RARRES2, and SEPTIN7 in association with GBM is reported in this study." (PMID 35327982, 2022).
cerebellar ataxia (1 paper, 2023). A neurological syndrome characterized by clumsy and uncoordinated movement of the limbs, trunk, and cranial muscles. "Autoantibodies against septin-5 are associated with non-paraneoplastic cerebellar ataxia, and autoantibodies against septin-7 with encephalopathy with prominent neuropsychiatric features." (PMID 36997937, 2023).
dementia (1 paper, 2017). Loss of intellectual abilities interfering with an individual's social and occupational functions. "We measured synaptophysin, PSD95, drebrin, SNAP-25, and septin 7 by ELISA in hippocampus and superior temporal gyrus from 103 adults aged <75 without dementia." (PMID 28731446, 2017).
Down syndrome (1 paper, 2014). "In neurodegenerative disease such as down syndrome, the diminished expression of septin 7 in diseased brain of human fetuses was connected to inhibition of synaptogenesis and synaptic function." (PMID 24614191, 2014).
Encephalopathy (1 paper, 2023). Encephalopathy is a term that means brain disease, damage, or malfunction. "Recently, anti-septin-7 autoantibodies were identified in patients with encephalopathy and myelopathy, suggesting that autoantibodies targeting different septins may be associated with distinct neurological phenotypes." (PMID 36997937, 2023).
endometrial cancer (1 paper, 2020). Primary or metastatic malignant neoplasm involving the endometrium (mucous membrane that lines the endometrial cavity). "In endometrial cancer, relative expression of septin-2 was highest, followed by septin-7." (PMID 32094384, 2020).
lung adenocarcinoma (1 paper, 2021). A carcinoma that arises from the lung and is characterized by the presence of malignant glandular epithelial cells. "While the presence of Septin7 seems indispensable for oncogenic Ras-induced lung-adenocarcinoma formation, further investigations in the Septin7 conditional knockout model is necessary to completely understand the role of septins in tumorigenesis." (PMID 35071236, 2021).
malignant glioma (1 paper, 2014). A grade III or grade IV glioma arising from the central nervous system. "In neoplasia, especially in the brain, septin 7 was reported to be involved in malignant glioma cell growth due to its inhibitory effect on cell proliferation, which may also be of importance in ERU, where cells with diminished septin 7 expression could be those proliferating." (PMID 24614191, 2014).
malignant mesothelioma (1 paper, 2022). A malignant neoplasm of the pleura or peritoneum, arising from mesothelial cells. "The mechanisms of CALB2 in malignant mesothelioma is through the binding of septin 7 on CALB2 promoter." (PMID 35963640, 2022).
Obesity (1 paper, 2025). Accumulation of substantial excess body fat. "•Septin-7 (SEPT7) plays a crucial role in regulating diet-induced obesity." (PMID 40015624, 2025).
osteosarcoma (1 paper, 2023). A usually aggressive malignant bone-forming mesenchymal neoplasm, predominantly affecting adolescents and young adults. "Furthermore, in human osteosarcoma U2-OS cells, Septin7 can maintain cell migration by modulating microtubule nucleation; thus, reduced Septin7 expression decreased the migration of these cells." (PMID 37508490, 2023).
uveitis (1 paper, 2014). An inflammatory process affecting a part of or the entire uvea. "Further analyses revealed T cells as the main cell type with decreased septin 7 abundance in equine recurrent uveitis." (PMID 24614191, 2014).
tumor (19 papers, 2014 to 2025). "Even though it was a known fact that septins are required for the proliferation of several tumor-derived epithelial cell lines and Septin7-deficient fibroblasts undergo obligate multinucleation in vitro, this is the first report establishing a clear role for septins in tumorigenesis in vivo." (PMID 35071236, 2021). "Additionally, we found other abundant proteins in PDAC samples implicated in cytoskeletal dynamics, cell motility and tumor progression such as TUBB4A, SEPTIN7, ARHGDIA, THBS1, and PPP1R12A, similar to reports from the literature." (PMID 41007761, 2025). "Septin-7 (SEPT7) inhibits matrix metalloproteinases and upregulates their negative regulators TIMP, and can therefore inhibit tumor growth and metastasis." (PMID 34771120, 2021).
cancer (13 papers, 2016 to 2024). A tumor composed of atypical neoplastic, often pleomorphic cells that invade other tissues. "Additional studies are needed to better evaluate the association of septin 7 and its genetic variability with both calretinin and cancer prognosis." (PMID 38203360, 2023). "In cancer-associated stroma, the expression of septin-2 and septin-9 was significantly upregulated, while septin-6 and septin-7 were unchanged." (PMID 32094384, 2020). "The opposite views about septin 7 in different kinds of cancer may be associated with the subcellular localization and post‐translational modifications of this protein." (PMID 29602250, 2018). "Next, we wanted to test if septin 7 was a downstream mediator for ERK3 function in promoting cancer cell motility." (PMID 32516969, 2020). "Indeed, our study revealed a role for the C-terminus tail in mediating the formation of ERK3/septin 7 complex and promoting cancer cell motility." (PMID 32516969, 2020). "To date, studies on the role of septin 7 in cancer are still rare." (PMID 31857849, 2019). "However, the molecular mechanisms of involvement of septin 7 in human disease, especially in the development of cancer, remain unclear." (PMID 29602250, 2018). "As septin 7 interacts with the C-terminal tail of ERK3, and we have demonstrated the importance of this region for invasiveness-promoting ability of ERK3, we sought to investigate the possible involvement of septin 7 in the role of ERK3 in cancer cells." (PMID 32516969, 2020).
infection (10 papers, 2014 to 2024). The state of being infected such as from the introduction of a foreign agent such as serum, vaccine, antigenic substance or organism. "For this reason, we employed SEPTIN7 siRNA as a tool for subsequent studies of septin function during infection." (PMID 29885024, 2018). "HeLa cells were treated with SEPTIN7 siRNA 48 hr prior to infection." (PMID 29885024, 2018).
SEPTIN7 also shares sentences with these, for which no sentence is quoted: hepatocellular carcinoma (4 papers); schizophrenia (3); bacterial infection (2); glioblastoma (2); melanoma (2); neurodegenerative disease (2); neurological diseases (2); viral infection (2); acute myeloid leukemia (1); breast ductal carcinoma in (1); cardiac failure (1); cardiomyopathies (1); chronic myelogenous leukemia (1); Cirrhosis (1); Cognitive impairment (1); colorectal tumors (1); COVID-19 (1); cyclosporiasis (1); cyst (1); diffuse large B-cell lymphoma (1); disseminated candidiasis (1); gastric cancer (1); Impaired glucose tolerance (1); Insulin resistance (1); invasive breast carcinoma (1); Jaundice (1); leukemia (1); lymphoma (1); mesothelioma (1); metabolic disease (1).
A further 11 diseases each share a sentence with SEPTIN7 in 1 paper.